KDM5A (lysine demethylase 5A)
Diseases named in the same sentence as KDM5A in open-access papers (continued):
Sharing a sentence is not in itself a finding about the gene and the disease.
gastric cancer (16 papers, 2013 to 2025). A primary or metastatic malignant neoplasm involving the stomach. "KDM5A was already shown as overexpressed in hepatocellular carcinoma, gastric cancer and glioblastoma and is thought to be required for promoting drug resistance in cancer cells." (PMID 37880235, 2023). "KDM5A is overexpressed in gastric cancer and increases cell proliferation and metastasis via repressing cyclin-dependent kinase inhibitors (CDKIs: p16, p21, and p27)." (PMID 33596982, 2021). "Previous reports have shown that KDM5A promoted cell proliferation in lung and gastric cancers by binding to the promoter of the genes p27 and p16, resulting in the demethylation of H3K4me3 and direct repression of p27 and p16." (PMID 30650517, 2019). "In gastric cancer cells and tumor associated macrophages, ELK4 might possibly activate lysine-specific demethylase 5A (KDM5A), which inhibits the expression of Praja 2 (PJA2), thus decreasing kinase suppressor of Ras 1 (KSR1)." (PMID 37381723, 2023). "We tried to elaborate the molecular mechanism of ETS-like transcription factor 4 (ELK4) affecting gastric cancer (GC) progression through M2 polarization of macrophages mediated by lysine-specific demethylase 5A (KDM5A)-Praja2 (PJA2)-kinase suppressor of ras 1 (KSR1) axis." (PMID 34372882, 2021). "Indeed, at least one of these enzymes is strictly associated with human cancer: KDM5A (also known as RBP2 and JARID1A) is over-expressed in gastric cancer, and its inhibition triggers cellular senescence of gastric cancer cells." (PMID 24489688, 2014). "We then investigated whether RB1 controls PGAM1 expression through KDM5A in gastric cancer cells." (PMID 40707487, 2025). "To elucidate the transcriptional regulation of RB1 via KDM5A, we conducted native elongating transcript cap analysis of gene expression (NET-CAGE) to analyze KDM5A-regulated genes in RB1-depleted gastric cancer cells." (PMID 40707487, 2025). "In gastric cancer, ELK4 plays a role in regulating the lysine-specific demethylase 5 (KDM5A)/Praja-2 (PJA2)/kinase suppressor of RAS1 (KSR1) axis." (PMID 37381723, 2023). "KDM5A depletion enhanced the promoter activities of p16 (INK4A), p21 (CIP1), and p27 (KIP1) and upregulated H3K4me3 levels in gastric cancer cells." (PMID 33578894, 2021). "In line with the oncogenic roles of KDM5A and KDM5B, suppression of KDM5A or KDM5B delays tumor formation, metastasis, and drug resistance in breast, lung, melanoma, and gastric cancers." (PMID 30080846, 2018). "Genetic variations in other genes (e.g. KDM5A, DNAH7, PLCE1, PSCA, PRKAA1, MUC1) reported to be specifically associated with gastric cancer initiation and progression were not investigated in the current study." (PMID 27929383, 2016). "Furthermore, KDM5A binds to the gene promoter of vascular endothelial growth factor (VEGF) to increase VEGF expression, thereby promoting angiogenesis that accelerates the growth of gastric cancer cells." (PMID 37880235, 2023). "The enhancement of gastric tumorigenesis by KDM5A was linked with transactivation of vascular endothelial growth factor (VEGF) expression and increased angiogenesis, suggesting that KDM5A overexpression and VEGF activation might play key functions in the progression of human gastric cancer." (PMID 33596982, 2021).
leukemia (16 papers, 2011 to 2025). A malignant (clonal) hematologic disorder, involving hematopoietic stem cells and characterized by the presence of primitive or atypical myeloid or lymphoid cells in the bone marrow and the blood. "KDM5A overexpression in leukemia associates with a poor prognosis." (PMID 37325571, 2023). "Integration of these data with results from a genome-wide CRISPR/Cas9 screen in NUP98::KDM5A-driven AML cells identifies a core set of 12 essential direct target genes which are critical for the survival of NUP98::KDM5A-driven leukemia cells." (PMID 40389480, 2025). "The majority of the 12 essential direct target genes also featured significantly higher H3K27ac marks in human NUP98::KDM5A leukemia cells from a PDX model compared to the mean signal of all other genes in this dataset." (PMID 40389480, 2025). "Our data show that CDK12 is crucial for the growth of NUP98::KDM5A-driven leukemia in vitro and in vivo and that small-molecule-mediated perturbation of CDK12 leads to a profound downregulation of genes involved in DNA repair, as reported in previous studies." (PMID 40389480, 2025). "Several of the direct NUP98::KDM5A target genes have been described to play roles in leukemia, such as CDKN2C29, CDKN1B30, NKX2-331, IGF2BP332,33, and MN134." (PMID 40389480, 2025). "It has been reported that KDM5A downregulates miR-21 expression in leukemia cells by directly binding to the promoter sequence of miR-21 and demethylating trimethylated H3K4 at the miR-21 locus." (PMID 33087165, 2020). "Downregulation of KDM5A has been reported to exert anti-leukemic effects, this implying potential therapeutic implications in leukemia treatment." (PMID 33167477, 2020). "Fusion of Nucleoporin 98 (NUP98) with the PHD containing part of JARID1A (or KDM5A - Lysine Demethylase 5A) drove alterations in leukemia." (PMID 30634442, 2019). "Following elucidation of the role of MLL translocations in the pathogenesis of leukemia came the discovery of a KDM5A leukemia oncogenic lesion, resulting in the deregulation of HOX and other lineage-specific genes." (PMID 21886846, 2011). "There is a consistent pattern of tissue specificity in the expression of MLL1 and KDM5A, two histone-modifying enzymes involved in leukemia." (PMID 21886846, 2011). "Strikingly, MLL1, a frequent leukemia translocation partner, displays an expression pattern similar to KDM5A, whose translocation was also shown to be involved in leukemia." (PMID 21886846, 2011). "This NUP98::KDM5A-driven model is fully dependent on sustained expression of the oncogenic driver, as its degradation leads to cell cycle arrest, differentiation, and apoptosis of leukemia cells." (PMID 40389480, 2025). "The role of NUP98 in leukemia development depends on its interaction with the PHD3 domain in KDM5A." (PMID 37325571, 2023). "Among AML patients, NUP98 fusion-driven leukemia patients (n = 11) showed even higher CDK12 expression, with highest levels detected in NUP98::KDM5A AML (n = 4)." (PMID 40389480, 2025). "Samples with the highest z-score values for KDM5A module and with the lowest z-score values for EZH2 module were found in leukemia samples of cluster 1, which was consistent with high expression of these modules in normal blood cell types." (PMID 21886846, 2011). "The difference in preferential expression of the H3K4me3 module in leukemia cells compared to normal blood cells suggests that this gene set may be deficient in methylation due to a distinct HDM/HMT gene expression signature, which includes a lack of correlation between KDM5A and MLL1 expression." (PMID 21886846, 2011).
glioblastoma (14 papers, 2017 to 2025). The most malignant astrocytic tumor (WHO grade IV). "Further investigations are needed to investigate the functional relationship between IDH mutation and other dioxygenase genes, such as KDM5A, a histone demethylase and a key factor for the resistance to temozolomide in glioblastoma." (PMID 35965532, 2022). "More often, overexpression of KDM5A is an oncogenic driver; high levels of KDM5A are observed across a wide variety of cancerous cells, including glioblastomas, breast, lung, and ovarian cancers." (PMID 40545232, 2025). "In glioblastoma and drug-tolerant persister cancer cells, expression of KDM5A confers drug resistance." (PMID 40545232, 2025). "For example, in temozolomide‐resistant glioblastoma cells, KDM5A expression is significantly boosted, while the inhibition of KDM5A expression promotes apoptosis." (PMID 37638338, 2023). "Recently, two KDMs, KDM3A in ovarian cancer and KDM5A in glioblastoma, were shown to confer resistance to chemotherapy." (PMID 29360266, 2018). "Similarly, an adaptive chromatin remodeling mechanism based on the activity of KDM5A/JARID1A has been described to drive resistance to kinase inhibitors in glioblastoma CSCs." (PMID 34298787, 2021). "KDM5A is highly expressed in drug-resistant cells such as temozolomide (TMZ)-resistant glioblastoma cells, and CPI-455 is more effective in TMZ-resistant glioblastoma cells than in TMZ-native cells." (PMID 36975603, 2023). "On the other hand KDM1, and more recently KDM6A/B were found to have a role in glioblastoma and KDM1, KDM4A, KDM5A and KDM5B are transiently overexpressed in GB cells that have acquired TMZ resistance." (PMID 28432280, 2017). "Specifically, increased activity of KDM5A leading to a reduction in histone 3 lysine 4 trimethylation (H3K4me3) has been shown to mediate resistance to gefitinib and cisplatin in NSCLC cells and to temozolomide in glioblastoma cells." (PMID 32195191, 2020). "The results showed that transcript levels of KDM5A/B/C were significantly increased in eight different types of cancer, including PDAC, gastric adenocarcinoma (STAD) and glioblastoma multiforme (GBM)." (PMID 37880235, 2023).
acute myeloid leukemia (10 papers, 2014 to 2025). Acute myeloid leukemia (AML) is a group of neoplasms arising from precursor cells committed to the myeloid cell-line differentiation. "PHD fingers have been shown to play a critical role in oncogenic drivers; for example, a chromosomal translocation in the PHD finger of PHF23 or lysine (K)-specific demethylase 5A (KDM5A) was implicated in acute myeloid leukemia." (PMID 28055972, 2017). "A chimeric fusion between the C-terminal PHD3 domain of KDM5A and nucleoporin 98 (NUP98) is frequently observed in acute myeloid leukemia (AML) cells and promotes malignant transformation." (PMID 40545232, 2025). "In acute myeloid leukemia (AML), KDM5A has been shown to form a fusion protein with a nucleoporin 98 gene (NUP98), and over-expression of this fusion protein alone is sufficient to induce AML in murine models." (PMID 24489688, 2014). "Interestingly, KDM5A/B/C were all reported to induce acute myeloid leukemia (LAML), while KDM5D has not been reported in literature to relate to LAML yet." (PMID 41431699, 2025).
melanoma (10 papers, 2012 to 2023). A malignant, usually aggressive tumor composed of atypical, neoplastic melanocytes. "RNA-seq data analysis showed that cell lines from lung-associated tumors, melanoma, lymphoma, and pancreatic cancer exhibited relatively high levels of KDM5A mRNA, compared to other cell lines." (PMID 37880235, 2023). "In melanoma, enhancing KDM5A activity improves the response of melanoma to immune checkpoint blockade programmed cell death protein 1 antibody." (PMID 33596982, 2021). "Notably, RNA-mediated KDM5A silencing confirmed that this histone demethylase allows for the maintenance of a reversible drug-tolerant state in human melanoma cells." (PMID 34575678, 2021). "In addition, retinoblastoma-binding protein 2-homolog 1 (RBP2-H1), a homolog protein with 54% identity with RBP2 (KDM5A), is downregulated in malignant melanoma." (PMID 33596982, 2021). "Interestingly, KDM5B overexpression reprogrammed melanoma cells to a CD34−, more drug-tolerant, phenotype, while KDM5B loss shifted melanoma cells to a more BRAFi-responsive CD34+ state, potentiating the pivotal role of KDM5A in modulating intratumoral heterogeneity in CM." (PMID 34575678, 2021). "KDM5A (JARID1A, RBP2) is a retinoblastoma RB-binding protein and mediates metastasis in estrogen receptor-negative breast cancers, while KDM5B (JARID1B or PLU-1) has roles in tumor maintenance, melanoma metastatic progression and resistance to cytotoxic agents and BRAF inhibitors." (PMID 28827149, 2017).
osteoporosis (10 papers, 2016 to 2025). A condition of reduced bone mass, with decreased cortical thickness and a decrease in the number and size of the trabeculae of cancellous bone (but normal chemical composition), resulting in increased fracture incidence. "Kdm5a inhibits bone formation in an osteoporosis mouse, and pretreatment with a Kdm5a inhibitor partially alleviates bone loss in osteoporosis." (PMID 33322579, 2020). "Pretreatment with KDM5A inhibitor JIB-04 partially rescues bone loss during osteoporosis by increasing the H3K4me3 level on the Runx2 promoter." (PMID 32963550, 2020). "More importantly, we found an inhibitory role of KDM5A in regulating bone formation in osteoporotic mice, and pretreatment with KDM5A inhibitor partly rescued the bone loss during osteoporosis." (PMID 27512956, 2016). "Taken together, these results indicate that BMP2 therapeutic inhibition of KDM5A (by shRNA or inhibitor of its methytranferase activity) was able to partly counteract the bone loss observed in osteoporosis." (PMID 27512956, 2016). "Additionally, KDM5A-mediated demethylation of H3K4me3 has been implicated in the etiology of osteoporosis." (PMID 41164311, 2025). "Subsequently, we explored the downstream mechanism of KDM5A regulating osteoporosis in MC3T3-E1 cells." (PMID 39972431, 2025). "Microarray analysis shows that KDM5A is upregulated in osteoporosis, which downregulates Runx2 by modifying its promoter H3K4 methylation and consequently causes impaired bone formation." (PMID 39972431, 2025). "KDM5A-mediated H3K4me3 demethylation is reported to participate in the pathogenesis of osteoporosis." (PMID 39972431, 2025). "In this study, the effects of TSG on osteogenic differentiation and maturation as well as the regulation of the KDM5A signaling pathway were studied in rat rBMSCs, to provide potential targets and candidate compounds for the treatment of osteoporosis." (PMID 35126937, 2022). "Histone methylation is regulated by lysine (K)-specific demethylases (Kdms), and KDM5A-mediated H3K4me3 demethylation has been shown to participate in the etiology of osteoporosis." (PMID 33553139, 2020). "A Gene Expression Omnibus (GEO) database of microarray analysis shows that elevation of Kdm5a is confirmed in osteoporosis MSC." (PMID 33322579, 2020). "By interrogating the microarray data from osteoporosis patients, we revealed an upregulation of the epigenetic modifying protein lysine (K)-specific demethylase 5A (KDM5A) and decreased Runt-related transcription factor 2 (RUNX2) expression." (PMID 27512956, 2016). "Knockdown of KDM5A restores osteoporotic bone mesenchymal stem cell (BMSC) lineage commitment by enhancing H3K4me3 level, and KDM5A-mediated H3K4me3 modification is implicated in the pathogenesis of osteoporosis." (PMID 39972431, 2025). "Therefore, KDM5A is closely related to the occurrence and development of a variety of diseases and is expected to be a new potential target for the treatment of osteoporosis." (PMID 35126937, 2022). "Moreover, bone loss in osteoporotic mice, was partly rescued following pre-treatment with a chemical inhibitor to KDM5A activity, demonstrating the regulatory role of KDM5A in osteoporosis in mice." (PMID 32794139, 2020). "Furthermore, the expression of miR-29b-3p was negatively correlated with KDM5A in osteoporosis samples." (PMID 33553139, 2020). "Herein, we identified bone marrow MSC (BMSC)-derived EVs harboring microRNA (miR)-29b-3p to regulate osteogenic differentiation through effects on the suppressor of cytokine signaling 1 (SOCS1)/nuclear factor (NF)-κB pathway via targeting of lysine demethylase 5A (KDM5A) in osteoporosis." (PMID 33553139, 2020). "Our results show, for the first time, that KDM5A-mediated H3K4me3 modification participated in the etiology of osteoporosis and may provide new strategies to improve the clinical efficacy of BMP2 in osteoporotic conditions." (PMID 27512956, 2016).
osteoporosis (continued). "Next, we used OVX-induced osteoporotic mouse model to test the role of KDM5A during osteoporosis." (PMID 27512956, 2016). "We demonstrated that Kdm5a-mediated H3K4me3 modification participates in the etiology of osteoporosis, which may provide new strategies to improve the clinical efficacy of BMP2 and to enhance bone formation under osteoporotic conditions." (PMID 27512956, 2016). "Further studies were focused on the role of KDM5A in osteoporosis." (PMID 27512956, 2016). "In this study, we wonder whether lysine (K)-specific demethylase 5A (KDM5A) functions as endogenous modulator of BMP2-induced osteogenic differentiation of MSCs in osteoporosis." (PMID 27512956, 2016). "miR-495 expression in femur tissues of osteoporosis mice and MC3T3-E1 cells was increased after interference of KDM5A." (PMID 39972431, 2025). "Furthermore, miR-495 expression in femur tissues of osteoporosis mice and MC3T3-E1 cells was increased after interference of KDM5A." (PMID 39972431, 2025). "For instance, in osteoporosis, the upregulated EZH2 and KDM5A and downregulated absent, small, or homeotic 1-like (ASH1L) genes suppress Wnt and Runx2 pathways by altering H3K4me3 and H3K27me3 levels." (PMID 32963550, 2020).
prostate carcinoma (9 papers, 2016 to 2024). A carcinoma that arises from epithelial cells of the prostate gland. "In prostate cancer, KDM5A is overexpressed and has been associated with a poor prognosis for patients." (PMID 39372390, 2024). "KDM5A enhances prostate cancer (PRAD) cell proliferation by downregulating miR-330-3p and activating COPB2 and AKT expression." (PMID 36835100, 2023). "This study revealed a possible synergistic effect of KDM5A and m6A regulators in the pathogenesis of prostate cancer." (PMID 35493099, 2022). "KDM5A can also promote the progression of prostate cancer through the KDM5A/miRNA-495/YTHDF2/m6A-MOB3B axis." (PMID 35493099, 2022). "This study was performed to elucidate the potential effects of KDM5A on prostate cancer (PCa) progression via the miR-495/YTHDF2/m6A-MOB3B axis." (PMID 33087165, 2020). "KDM5A silencing inhibits the proliferation and migration of prostate cancer cells." (PMID 36835100, 2023). "In addition, compared with that in normal prostate tissue, the expression of KDM5A in prostate cancer tissue was upregulated." (PMID 35493099, 2022). "However, the role of KDM5A in NEtD of prostate cancer remains uncovered." (PMID 39372390, 2024). "Furthermore, lysine demethylase 5A (KDM5A), a histone demethylase, is overexpressed in prostate cancer." (PMID 36835100, 2023). "For example, KDM5A histone lysine demethylase inhibitor CPI-455 was reported to induce apoptosis and inhibit the proliferation of many tumor cells, such as cervical and prostate cancer." (PMID 36396833, 2022).